RHOA (ras homolog family member A)
Diseases named in the same sentence as RHOA in open-access papers (continued):
Sharing a sentence is not in itself a finding about the gene and the disease.
lymphoma (42 papers, 2012 to 2025). A malignant (clonal) proliferation of B- lymphocytes or T- lymphocytes which involves the lymph nodes, bone marrow and/or extranodal sites. "The p.Gly17Val RHOA (G17V) mutation is commonly found in these lymphomas and can aid diagnosis, offering faster results, especially in patients with specific clinical features like lymphadenopathy, fever, and skin rash." (PMID 40347078, 2025). "A genetic hallmark of this lymphoma is the frequent occurrence of the RHOA mutation G17V in neoplastic cells, which is observed in around 60% of patients." (PMID 37370838, 2023). "Together these data strongly support a role for RhoA-G17V as a driving mutation in nodal TFH lymphomas but also speak to the requirement for concomitant TET2 loss in the hematopoietic compartment to promote lymphomagenesis." (PMID 37841428, 2023). "Since resemblance with AITL was striking, these authors analyzed the Tfh plck-GAPDH lymphoma cells for mutations in RhoA, Tet2, Idh2, and Dmt3a, frequently mutated in these patients." (PMID 32796826, 2020). "RHOA mutations are seen at relatively high frequencies in other lymphomas such as ATLL and pediatric Burkitt’s lymphoma, and diffuse-type gastric cancer." (PMID 32704161, 2020). "Further studies on the biological significance of these mutations suggested a driver role for RHOA in the pathogenesis of these lymphomas." (PMID 31248017, 2019). "The results demonstrated that patients harboring an RHOA mutation in their lymphoma showed a favorable PFS and OS (P < 0.05)." (PMID 31403034, 2019). "More specifically, in human lymphomas recurrent somatic mutations have been reported only for the GTPase RHOA and for the atypical GTPase RHOH, whereas somatic mutations affecting RAC proteins or CDC42 have been described in solid tumors." (PMID 31248017, 2019). "In several recent publications the pathophysiological importance of mutations of the RhoA GTP-binding pocket region for T lymphoma has been elucidated." (PMID 31319592, 2019). "Further biological studies with appropriate in vitro and in vivo models will help to elucidate the functional significance of gain- and loss-of-function mutations of RHOA in human lymphoma." (PMID 31248017, 2019). "TBILA is upregulated by the TGF‐β classical signalling pathway and promotes human germinal centre‐associated lymphoma expression by binding with the Smad transcription factor complex, thereby enhancing RhoA activation." (PMID 30499165, 2019). "Two whole-exome sequencing studies of human lymphomas found recurrent Gly17Val mutations in RhoA which confer a dominant negative or loss of function phenotype." (PMID 26030593, 2015). "One difficulty, however, is that RHOA mutation allele frequencies in these lymphomas are generally as low as <0.2 or often <0.1, reflecting low tumor cell content." (PMID 25310466, 2014). "Gcsam (MGI:102969), formerly known as Gcet2, is a regulator of the RhoA signaling pathway that negatively regulates lymphocyte mobility and whose expression is associated with increased survival in at least two types of lymphoma." (PMID 24004649, 2013). "The mutation RhoA-G17V (a missense mutation leading to the change of the amino acid glycine on position 17 to valine) is common in CD4+ T-cells in lymphoma and is associated with autoimmunity, hyper-responsiveness of T-cells, and excessive TCR signaling via the Rho-GEF Vav1." (PMID 34359851, 2021). "Indeed, the recent implementation of deep sequencing strategies revealed recurrent mutations of RhoA in PTCLs, suggesting a driver role for RhoA in the development of these lymphomas." (PMID 33928032, 2021). "Furthermore, RhoA signaling has been identified as a target in case of autoimmune diseases as well as lymphomas and leukemias caused by mutations of components of this signaling pathway." (PMID 31319592, 2019).
lymphoma (continued). "RHOA mutations have also been found in lymphomas of B-cell origin." (PMID 31248017, 2019). "Overall, even if historically RHOA was described as a molecule with pro-oncogenic functions because it is frequently overexpressed in human tumors and associated with tumor progression, recent findings on RHOA mutations describe a more complex and heterogeneous landscape, at least in human lymphoma." (PMID 31248017, 2019). "Regarding genomic alterations, RhoA mutations have been reported in lymphomas." (PMID 30209389, 2018). "Of note, in AITL and related lymphomas, RHOA mutations were accompanied by TET2 mutations, suggesting that TET2 and subsequent RHOA mutations may pave the way for T-cell transformation." (PMID 29148847, 2018). "Notably, the p.Gly17Val RHOA (G17V) mutation is commonly associated with Tfh lymphomas, including angioimmunoblastic T‐cell lymphoma, suggesting that testing for the G17V mutation may serve as a valuable diagnostic tool." (PMID 40347078, 2025). "In mouse models, TET2 deficiency and RHOA mutations promote TFH polarization via ICOS/PI3K-MAPK signaling, leading to lymphoma development, while IDH2 further augments this process through TET inhibition." (PMID 41295262, 2025). "In difficult cases, the presence of RHOA and/or IDH2 mutations supports the diagnosis of TFH lymphoma." (PMID 37747559, 2024). "Several studies have highlighted the characteristic mutational landscape of TFH lymphomas, which typically associates mutations in epigenetic regulators (TET2, DNMT3A, and IDH2), RHOA G17V, and alterations in the T-cell receptor (TCR) signaling pathway." (PMID 37500795, 2023). "In malignant lymphomas, mutations can influence the correct assembly of the cytoskeleton and thus the ability to migrate (e.g., ROCK1 mutation in Hodgkin lymphoma, RHOA mutations in AITL and DLBCL, and ACTB mutations in DLBCL)." (PMID 34680356, 2021). "Mutations related to the RAS family (RHOA) and those related to epigenetic regulators (IDH2, DNMT3A, and TET2) were shown mainly in AITL and other TFH lymphomas." (PMID 33990228, 2021). "While the G17V mutation confers a tumor suppressor function to RhoA in AITL, additional mutations in this gene have been reported in other PTCLs subtypes like Adult T-cell leukemia/lymphoma (ATLL)." (PMID 33928032, 2021). "More importantly, it is reported that FAK and RhoA played important role in modulating the motility of malignant lymphoma cells." (PMID 30814910, 2019). "Gain-of-function mutations of RHOA have been described at lower frequencies in human tumors, such as RHOA A161V/P in bladder urothelial cancer and RHOA C16 and A161V/P in adult T-cell leukemia/lymphoma (see specific paragraph in this review)." (PMID 31248017, 2019). "Physiologically this protein inhibits lymphocyte and lymphoma cell motility by activating on the RhoA signaling cascade and interacting with actin and myosin proteins." (PMID 25232701, 2014). "Recently it was demonstrated that HGAL was specifically targeted by miR-155 leading to a decreasing of RhoA activation and increasing of spontaneous and chemoattractant-induced lymphoma cell motility." (PMID 25232701, 2014). "The mutational landscape of TFH lymphoma includes genes involved in epigenetic pathways such as TET2 (up to 90%), IDH2 (20–45%), and DNMT3A (20–30%), mutations in the small GTPase RHOA (50–70%) and mutations in the TR signaling pathway including PLCG1, CD28, FYN, and VAV1." (PMID 37747559, 2024). "In these various murine models, RhoA-G17V overexpression in T cells promoted TFH proliferation/expansion and the concomitant expression in the setting of hematopoietic TET2 deficiency led to the development of TFH lymphomas with varying penetrance." (PMID 37841428, 2023). "Our findings showing up-regulation of RHOA/RAC/PAK signalling in Eμ-Myc/RelAT505A lymphomas, suggests that this pathway may function as a potential mechanism of CHK1i resistance bypass signalling." (PMID 36240067, 2022).
lymphoma (continued). "Through analysing our RNA-Seq dataset for the presence of intrinsically up-regulated gene expression signatures in Eμ-Myc/RelAT505A lymphomas, we discovered elevated expression of genes encoding components of the RAC1/RHOA signalling pathway, something also seen in Eμ-Myc/c-Rel−/− lymphomas." (PMID 36240067, 2022). "Notably, mutations related to the RAS family (RHOA) and those related to epigenetic regulators (IDH2, DNMT3A, and TET2) were found mainly in AITL and other TFH lymphomas." (PMID 33990228, 2021). "Despite the fact that RHOA may play certain role in T-cell biology in lymphomas, the involvement of RHOA in T-cell function in the context of CRC/CAC has not been explored to date to our knowledge." (PMID 33406731, 2021). "However, the current knowledge is not sufficient to support the role of RhoA mutations as a driving event in lymphomas." (PMID 30209389, 2018). "In conclusion, our results suggest that the characteristic presentation of AITL with early, widespread dissemination of lymphoma cells is not the result of an enhanced migration capacity due to the RHOA-G17V mutation; instead, this feature may rather be related to extracellular matrix remodelling." (PMID 37370838, 2023). "As reported in other studies, the representative genetic alterations to induce a robust T follicular helper phenotype (RHOA, IDH2, and DNMT3A) of AITL also appeared in other TFH lymphomas." (PMID 33990228, 2021). "In addition to frequent somatic mutations in RHOA and epigenetic modifiers, several studies have shown frequent alterations affecting TCR signaling-related genes, including CD28, FYN, PLCγ1 and VAV1 in cutaneous T-cell lymphomas, AITL and adult T cell leukemia/lymphoma." (PMID 30814910, 2019). "In this review we present the latest advances in the field with particular focus on the role of the most studied typical RHO GTPases such as CDC42, RAC1, and RHOA and the atypical RHOH in the initiation or progression of human lymphomas." (PMID 31248017, 2019). "Though the AITL hotspot mutation RhoAG17V was not present, two mutations in RhoA were found, 1 point mutation at position 37 (RhoAT37M) present in all tumors and an INDEL frameshift mutation in 4/15 lymphomas." (PMID 32796826, 2020). "Neither manual examination, STRING analysis nor functional annotation clustering using our phosphoproteomic data gave any further insights into whether RHOA or RAC1 signalling might be up-regulated in Eμ-Myc/RelAT505A lymphomas (not shown)." (PMID 36240067, 2022). "Adoptive transfer of wild-type or TET2-deficient T cells retrovirally transduced to overexpress RhoA-G17V into T-cell deficient murine hosts resulted in CD4+ T cell expansion, disruption of peripheral T cell homeostasis and eventually lethal inflammation but no lymphoma was noted." (PMID 37841428, 2023). "Importantly, among Tfh lymphomas, IDH2R172 mutations are mostly confined to AITL and are rare in FTCL and PTCL-NOS with Tfh phenotype or GEP, unlike recurrent mutations in TET2, DNMT3A, and RHOA, which are common to all types of Tfh lymphomas." (PMID 32704161, 2020). "In nTFHL-AI particularly, RHOA and IDH2 show promise as MRD markers because they are not present in pre-lymphoma clones." (PMID 41295262, 2025).
atherosclerosis (39 papers, 2008 to 2025). A disease characterized by the build-up of fatty material and calcium deposition in the arterial wall resulting in partial or complete occlusion of the arterial lumen. "They concluded that GGTase-I deficiency activates RhoA leading to the increase of reverse cholesterol transport (cholesterol efflux) from the macrophages and the inhibition of atherosclerosis." (PMID 33379334, 2020). "Additionally, RBP4 regulates the phenotypic transformation of vascular smooth muscle cells via the Ras homolog family member A/Rho-associated coiled-coil containing protein kinase 1 (RhoA/ROCK1) signaling pathway in atherosclerosis." (PMID 39981296, 2025). "The observed plaque regression in TG/ApoE mice demonstrates the potential for therapeutic interventions targeting RhoA or macrophage polarization to halt or reverse atherosclerosis." (PMID 37628966, 2023). "Multiple research has demonstrated an association between the activation of the RhoA/ROCK1 pathway and the onset and progression of atherosclerosis." (PMID 37278388, 2023). "It has been suggested that the YAP/TAZ is indispensable for signaling in the response to shear stress and promotes atherosclerosis in response to the disturbed flow, which is dependent on RhoA-mediated signaling." (PMID 36675179, 2023). "As the RhoA/ROCK1 pathway is pivotal in atherosclerosis progression, and mitochondrial dysfunction is a recognized pathogenic mechanism of atherosclerosis, the relationship between the RhoA/ROCK1 pathway and mitochondrial dynamics has attracted our attention." (PMID 37278388, 2023). "They highlight the crucial roles of macrophages and RhoA signaling in atherosclerosis development and regression." (PMID 37628966, 2023). "Another promising therapeutic for the treatment of atherosclerosis is the RhoA/ROCK inhibitor fasudil." (PMID 36206080, 2022). "The activation of RhoA/Rho kinase (ROCK) pathway is linked with OS, atherosclerosis, and cardiovascular-renal remodeling." (PMID 35873439, 2022). "Axis formed by integrin β3 (ITGβ3)-Ras homolog gene family, member A (RhoA), and Yes-associated protein (YAP) plays an important role in atherosclerosis." (PMID 33818281, 2021). "In summary, salidroside exerted significant barrier-protective and anti-atherosclerosis effects against IH via the cAMP/PKA/RhoA signaling pathway." (PMID 34504429, 2021). "Below, we describe why and how the lipids accumulate in the arterial wall, what are the roles of macrophages in lipid accumulation and the development and progression of atherosclerosis, and how the RhoA pathway regulates some of these processes." (PMID 33379334, 2020). "Other studies of the significance of the RhoA and Rac1 prenylation for atherosclerosis development have focused on the role of the unmodified and geranylgeranylated RhoA and Rac1 in the atherosclerosis progression in the rabbit model." (PMID 33379334, 2020). "It seems that the beneficial or unfavorable effect of RhoA on atherosclerosis depends on the cellular context." (PMID 33379334, 2020). "The issue of farnesylation and geranylgeranylation of RhoA, Rac1, and CDc42 in atherosclerosis is important for the therapeutic use of the lipid-lowering agents, statins, in the prevention and reduction of atherosclerosis." (PMID 33379334, 2020). "In atherosclerosis, macrophage deletion of G12/13 reduces inflammatory potential and RhoA activation." (PMID 31174369, 2019). "The activation of RhoA/Rho kinase pathway is recognized to be related with OxSt and involved in atherosclerosis and cardiovascular-renal remodeling." (PMID 30261035, 2018). "Arterial stiffening accompanies both aging and atherosclerosis, and age-related stiffening of the arterial intima increases RhoA activity and cell contractility contributing to increased endothelium permeability." (PMID 26761203, 2016).
atherosclerosis (continued). "Our present data suggest that HMGB-1 activates MT1-MMP through RAGE lead ing to RhoA/Rac1 activation, NF-κB phosphorylation and TF protein upregulation as a pathology of the progression of atherosclerosis and vascular endothelial dysfunction." (PMID 25490770, 2014). "Drugs that could inhibit the RhoA/ROCK1 pathway were expected to become new targets for treating atherosclerosis with P. gingivalis infection." (PMID 37278388, 2023). "Targeting RhoA-specific p190RhoGEF expression or RhoA signaling in macrophages could be explored as a therapeutic strategy to modulate atherosclerosis progression in humans." (PMID 37628966, 2023). "Also, change of matrix stiffness during atherosclerosis development regulates ECs through the RhoA/ROCK pathway and MAPK pathway." (PMID 35599845, 2022). "Such RhoA inhibition-based therapy may be potentially applicable for the inhibition of deleterious functions of macrophages in the atherosclerosis." (PMID 33379334, 2020). "Furthermore, there is evidence that KRIT1 silencing impacts Delta-Notch and RhoA/ROCK signaling pathways, which are clearly implicated in ED and atherosclerosis." (PMID 31590384, 2019). "Therefore, in the present study, we hypothesized that salidroside protects the integrity of endothelial barriers and alleviates CIH-aggravated atherosclerosis through effects on cAMP/PKA/RhoA signaling." (PMID 34504429, 2021). "Administration of exogenous NO for the treatment of cardiovascular diseases with increased ROCK activities, such as stable angina pectoris or vasospastic angina, may have beneficial effects in the prevention of atherosclerosis through inhibition of RhoA/ROCK signaling." (PMID 25280018, 2014). "Studies have shown that the junctional cadherin 5-related protein (JCAD) interacts with LATS2 via RhoA, resulting in an increased YAP activity and ECs dysfunction, leading to atherosclerosis." (PMID 36675179, 2023). "In atherosclerosis, activation of HMGB1 and RhoA/Rac1 is closely related to vascular inflammation induced by NF-κB phosphorylation in endothelial cells." (PMID 35674581, 2022). "Several mechanisms that connect shear stress and atherosclerosis have been described, involving PECAM-1, eNOS, and RhoA." (PMID 36292250, 2022). "The RhoA/ROCK pathway has different and, often, depending on the cellular context, contradictory effects on the cardiovascular system and atherosclerosis." (PMID 33379334, 2020). "Therefore, increasing RhoA activation may represent a novel pathway that may be exploited therapeutically, and increasing macrophage-specific activation of RhoA was shown to reduce atherosclerosis in mice." (PMID 28814641, 2017). "However, chronic upregulation of O-GlcNAc in VSMCs was proved to be related to vascular contractile dysfunction via the RhoA-ROCK pathway and subsequent arterial stiffness and atherosclerosis." (PMID 41480156, 2025). "In addition, the RhoA/ROCK pathway plays a vital role in the formation of plaques and accelerates the process of atherosclerosis by mediating the differentiation of monocytes into macrophages and then secreting a series of inflammatory mediators." (PMID 37278388, 2023). "Reports have shown that RhoA, Rac1, and CDC42 play important roles in atherosclerosis." (PMID 36185329, 2022). "Therefore, not only decreasing RhoA isoprenylation is critical, inhibiting ROCK activity is also crucial in preventing atherosclerosis development and reducing cardiovascular events." (PMID 26018523, 2015).